CTSB (cathepsin B)
Diseases named in the same sentence as CTSB in open-access papers (continued):
Sharing a sentence is not in itself a finding about the gene and the disease.
melanoma (continued). "The involvement of cathepsin L in tumor progression is less evident than for cathepsin B but its contribution to the invasive and metastatic potential of malignant cells such as oncogenically transformed fibroblasts and melanoma cells has been demonstrated." (PMID 26157794, 2015). "Like LDH, the combination of IL-8 and Cathepsin B serum levels can be used to predict the medium term mortality (3–5 years) of melanoma patients." (PMID 21673904, 2011). "Here we show that, after using a special buffer to eliminate the serum interference, IL-8 and cathepsin B levels were significantly elevated in melanoma patients (p < 0.05)." (PMID 21673904, 2011). "We have previously shown that slight acidification of the microenvironment of a variety of tumors (melanoma, colon, and breast) increases secretion and activity of cathepsin B and proteolysis of type IV collagen." (PMID 22093547, 2011). "We have shown that, after the elimination of serum interference, IL-8 and cathepsin B were significantly elevated in melanoma." (PMID 21673904, 2011). "More importantly, the combination of IL-8 and cathepsin B were also studied as a prognosis marker for melanoma mortality." (PMID 21673904, 2011). "In a proteomic analysis, elevated cathepsin B level was detected from the sera of mice carrying human melanoma xenografts." (PMID 21673904, 2011). "In fact, a significantly higher expression of cathepsin B at the cell surface of metastatic melanoma cell lines (p = 0.0087) was observed." (PMID 20684763, 2010). "Legumain, cathepsin B and L were expressed and active in most of the cell lines, although at low levels in the melanomas expressing cystatin E/M." (PMID 20074384, 2010). "For cathepsin B, most of the positive melanoma lines expressed the 25 kD molecular weight form, whereas a few cell lines also showed lower levels of the 30 kD form." (PMID 20074384, 2010). "In conclusion, our paper suggests a role for cathepsin B in tumor growth and in metastatic potential of human melanoma." (PMID 20684763, 2010). "The relationship between in vitro invasiveness and cathepsin B localization at the plasma membrane was then analyzed in four different cell lines from both primary and metastatic human melanomas." (PMID 20684763, 2010). "In the same vein, we observed that the presence of specific antibodies to cathepsin B in the culture medium significantly decreased the percentage of metastatic melanoma cells able to cross through a basement membrane matrix, i.e. Matrigel." (PMID 20684763, 2010). "The IFI30 expression, in melanoma and squamous cell carcinoma, has been shown to enhance antigen presentation and to activate CTSB, which is required for osteoclast fusion during differentiation." (PMID 20551950, 2010). "We analyzed the total amount of cathepsin B, D and L in four cell lines derived from human metastatic melanomas (MM1-MM4) and in four cell lines derived from primary lesions (PM1-PM4) by means of Western blotting." (PMID 20684763, 2010). "In the present work we investigated in both in vitro and in vivo systems the effects of cathepsin B, D and L inhibitors, i.e. chemical and biological (e.g. antibodies) in modulating metastatic melanoma cells invasiveness." (PMID 20684763, 2010). "Nevertheless, an intracellular role for cathepsin B in matrix degradation has been identified, and also, three forms of extracellularly active cathepsin B and two forms of active cathepsin L have been described in the highly invasive melanoma cell line MV3." (PMID 17620116, 2007). "Autophagy and cathepsin B targeted therapy was reported to improve melanoma treatment." (PMID 33335896, 2020). "Overexpressing cathepsin B did not lead to inhibition of CEP activity, 20 mg/L CEP could also decrease cathepsin B overexpressed in melanoma cells." (PMID 33335896, 2020).
melanoma (continued). "Further research on melanoma, as well as on other tumor models, will however be crucial to clarify these points before generating therapeutic strategies based on the use of available or novel potential inhibitors of cathepsin B activity." (PMID 20684763, 2010). "As far as the intracellular content of cystatin C was concerned, flow cytometry analysis revealed a modest, but significantly (p < 0.01) higher amount of this physiological cathepsin B inhibitor in cell lines from primary melanoma in comparison to those from metastatic lesions." (PMID 20684763, 2010). "In our experimental model, in spite of the higher amount of cathepsin B mRNA in metastatic melanoma cell lines in comparison to primary melanoma cell lines, we observed that protein cathepsin B content was higher in primary melanoma than in metastatic melanoma cell lines." (PMID 20684763, 2010). "Although the activities of cathepsin B and L in melanoma and other tumor types are well documented, the expression and activity of legumain in melanoma is relatively unknown." (PMID 20074384, 2010). "Additional effects cystatin on melanoma cell metastasis might have been expected if our melanoma cystatin over-expressing clones had secreted cystatin C. Multiple roles extracellular cathepsin B have been suggested, including matrix degradation." (PMID 15904519, 2005). "Here, the authors show that on contact with these immune cells melanoma cells can resist T cell cytotoxicity by modulating the trafficking of their lysosomal compartment, this results in the degradation of the T cell protein perforin by the protease cathepsin B." (PMID 26940455, 2016). "Acidosis has also been demonstrated to increase the secretion of proteases such as cathepsin B in melanoma cells and matrix metalloproteinase-9 (MMP-9) in human osteosarcoma cells, which may facilitate the degradation of extracellular matrix proteins and subsequently accelerate tumor cell invasion." (PMID 24367336, 2013). "Cathepsin B demonstrated a promoting effect on BCC (OR = 1.092, 95% CI: 1.026–1.163, P < .05) and a tendency for non-melanoma (OR = 1.182, 95% CI: 0.995–1.404, P = .06)." (PMID 39312365, 2024). "A study showed that Abl/Arg promoted CTSB secretion through controlling the transcription factors with epithelial mesenchymal transition (EMT), invasion and therapeutic resistance in melanoma cells." (PMID 36132145, 2022). "Cathepsin B (CTSB) and cathepsin D (CTSD) are key mediators of lysosomal-mediated cell death and cathepsin inhibitors reduce human melanoma growth and lung metastasis." (PMID 36430634, 2022). "In our previous work 46, we have validated the relevance of cathepsin B (CTSB) by demonstrating its over-activation in murine and human melanoma cells compared to that in normal skin." (PMID 36168618, 2022). "Cathepsin B regulates the production/signaling of TGF-β and promotes fibroblast activation which in turn promotes invasive growth of melanoma cells." (PMID 33335896, 2020). "This was not surprising as the inhibition of Cathepsin B was shown to reduce tumor growth and metastatic potential of melanoma, both in vitro and in vivo." (PMID 41155412, 2025). "In the melanoma cell line WM793, CTSB activity is important for TGF-β production and secretion." (PMID 37576397, 2023). "By treating A-07, D-12, and T-22 human melanoma cells with media buffered to pH 6.8, several proteins such as MMP-2, MMP-9, cathepsin B, cathepsin L, VEGF-A, and IL-8 are upregulated and contribute to increased experimental lung metastasis post tail vein injections in athymic nude mice." (PMID 24367336, 2013). "In melanoma, cathepsin B and L activities are increased relative to normal skin, and both the cysteine proteases conferred a metastatic phenotype." (PMID 20074384, 2010).
melanoma (continued). "It appeared evident that the amount of cathepsin B resulted higher in cells from primary melanomas rather than in those from metastatic ones." (PMID 20684763, 2010). "Indeed, a previous study showed that acidic pH promotes experimental pulmonary metastasis of human melanoma cells in athymic nude mice by up-regulating the expression of the proteolytic enzymes MMP-2, MMP-9, cathepsin B, and cathepsin L and the proangiogenic factors VEGF-A and IL-8." (PMID 30836626, 2019). "Conversely, the evaluation of surface expression of cathepsins by flow cytometry revealed that cathepsin B was higher in cell lines from metastatic melanomas (MM1 and MM2 as representative cell lines) than in cell lines derived from primary melanomas (PM1 and PM2 as representative cell lines)." (PMID 20684763, 2010). "We have observed expression of cystatin E/M, legumain, cathepsin B and L in multiple melanoma cell lines, and an inverse correlation between secreted levels of the cysteine protease inhibitor and cellular activities of legumain and cathepsin B (but not cathepsin L) was detected." (PMID 20074384, 2010). "The block of cathepsin B activity via antibody administration, unlike that of chemical compounds and siRNA, could impair metastatic melanoma cell dissemination certainly exerting their activity at extracellular level." (PMID 20684763, 2010). "However, we could not detect any changes in cathepsin B activity when over-expressing cystatin E/M in melanoma cells." (PMID 20074384, 2010). "Quantitative analysis of transcripts for cathepsin genes CTSA, CTSB, and CTSD corroborated that ectopic expression of LAMP-2C in melanoma cells did not increase the expression of these lysosomal enzyme mRNAs." (PMID 30211163, 2018).
glioblastoma (43 papers, 2012 to 2025). The most malignant astrocytic tumor (WHO grade IV). "Prior studies in glioblastoma cells showed that GST-Mda-7 treatment caused cell killing via a toxic form of autophagy associated with cathepsin B." (PMID 37280571, 2023). "Cathepsin B and Tenascin-C are highly expressed in malignant anaplastic astrocytomas and glioblastomas when compared to normal brain tissues and are associated with tumor neovessels." (PMID 36980765, 2023). "The relevance of our findings is underscored by the fact that cathepsin B activity is typically increased under hypoxia, which is a hallmark of glioblastoma." (PMID 24743710, 2014). "Cathepsin B (Cat B), a lysosomal protease overexpressed in tumors, including glioblastoma, recognizes the valine-alanine (VA) dipeptide sequence, leading to linker cleavage and drug release in the tumor microenvironment." (PMID 40574045, 2025). "Cathepsin B is an enzyme that is predominantly found in microvascular endothelial cells surrounding human glioblastoma and prostate carcinomas." (PMID 38611849, 2024). "Other investigations reported that the expression of cathepsin B was upregulated in glioblastoma to provide resistance to RT by enhancing the homologous recombination." (PMID 38069428, 2023). "Complement C1q tumor necrosis factor-related protein 8 (CTRP8) interacts with RXFP1 and induces the production and secretion of cathepsin B in glioblastoma cells, leading to laminin degradation and glioblastoma dissemination." (PMID 32727598, 2020). "Cathepsin B (Cat B) and cathepsin (Cat L) were also strongly expressed in various cell clusters within the glioblastoma microenvironment." (PMID 33312949, 2020). "Glioblastoma-associated microglia/macrophages (GAM) displayed pronounced CD68 and cathepsin B (CTSB) upregulation, characteristic of an activated state." (PMID 31060205, 2019). "The expression and enzyme activity of cathepsin B and D gradually increased in high-grade glioblastoma." (PMID 28106765, 2017). "To further analyze H-1PV interactions with glioblastoma cells and their microenvironment, we examined in resected tissues the expression of cathepsin B (CTSB)." (PMID 28967558, 2017). "We therefore evaluated the effect of cathepsin B inhibitors, compound 17 and nitroxoline on the migration of tumor cells out of co-cultured glioblastoma-MSCs spheroids." (PMID 28938624, 2017). "Our results are in line with the upregulated cathepsin B levels in glioblastoma U373 cells on direct cell-to-cell interactions with MSCs." (PMID 28938624, 2017). "In particular, we assessed the activity of Cathepsin B in U87 glioblastoma cells by ADPL, and found similar results to those observed for serine hydrolases." (PMID 29176560, 2017). "Highest LC3B (5A*), p62 (5B*), LAMP2 (5C*) and CTSB (5D*) levels were seen in close vicinity of pseudopalisading necrosis in human glioblastomas, frequently decreasing within a 100–500 μm distance from the border of the pseudopalisading cells." (PMID 26956048, 2016). "WHO grade III astrocytomas also showed decreased CTSB levels as compared to WHO grade IV glioblastoma." (PMID 26956048, 2016). "Cathepsin B is rather prominently upregulated in glioblastoma and promotes glioblastoma growth by contributing to matrix dissolution, Bcl-2 maintenance, and AKT activation." (PMID 25211298, 2014). "Experimental reduction of cathepsin B inhibited glioblastoma growth and invasion in rodent glioblastoma models." (PMID 23594434, 2013). "Auranofin inhibits cathepsin B and was previously suggested as a glioblastoma treatment adjunct on that basis." (PMID 23594434, 2013). "Two independent groups found that heavier cathepsin B immunohistochemical staining predicts shorter glioblastoma OS." (PMID 23594434, 2013). "Lysosomal Cathepsin B is highly expressed in malignant glial cells and endothelial cells of vascularized glioblastoma, an indication of a shorter survival time." (PMID 22995409, 2012).
glioblastoma (continued). "Our hypothesis is that upon delivery to glioblastoma cells, T7-SN-38-rucaparib undergoes cleavage by cathepsin B, liberating free SN-38 and rucaparib." (PMID 40574045, 2025). "Interestingly, a recent report has revealed an unexpected role for CtsB in glioblastoma resistance to radiation." (PMID 39851495, 2025). "The authors demonstrated that CtsB is upregulated in glioblastoma cells in response to radiation, contributing to radioresistance by promoting DNA homologous recombination, although the molecular details are still unknown." (PMID 39851495, 2025). "Similarly, another study showed that inhibition of CTSB expression can inhibit glioblastoma (GBM)-induced neovascularization." (PMID 37576397, 2023). "It was found that CTSB was negatively associated with both OS and DFS in brain low-grade glioma (LGG) and mesothelioma (MESO), and negatively correlated with OS in BLCA, breast invasive carcinoma, and glioblastoma multiforme (GBM)." (PMID 35155389, 2022). "In a phase I/II clinical trial, ParvOryx01, a rat H-1 parvovirus (H-1PV) for the treatment of recurrent glioblastoma patients, promoted an immunogenic TME, inducing accumulation of activated TAMs in CD40L-positive glioblastoma regions and up-regulation of cathepsin B and iNOS expression in TAMs." (PMID 34680425, 2021). "Cheng and colleagues found that treatment with caffeine could inhibit the progression of human glioblastoma by suppressing invasion and growth through cathepsin B and MAPK signaling." (PMID 34946741, 2021). "However, high expression of CTSB has been related to poor survival in glioblastoma patients and involved in promoting temozolomide intrinsic resistance." (PMID 33557274, 2021). "In addition, cathepsin B has been found to be involved in tumor initiation, migration, and drug resistance of glioblastoma stem cells and prostate cancer stem cells." (PMID 34272452, 2021). "Compared with the control primary glioblastoma, the first recurrence (resected at day nine post-treatment) showed a clear induction of both cathepsin B and iNOS expression in TAM cells, which persisted and even increased in the second recurrence at two months after virus application." (PMID 29244745, 2017). "Cathepsin B is an important element of glioblastoma cell invasion along Scherer's tracts." (PMID 23594434, 2013). "While the exact composition of the secretome is largely unknown, related research has identified of insulin-like and opioid growth factors or proteins such as ADAM9, cathepsin B and neuropilin-1 as key components of the secretome of head and neck tumor or glioblastoma cells." (PMID 38092866, 2023). "As a direct result of their abortive parvovirus infection and/or indirectly, via proinflammatory mediators released by infected tumor cells, microglia/macrophages get activated and may exert toxic effects on neighboring glioblastoma cells through cathepsin B and NO release." (PMID 29244745, 2017). "Binding of the leucine-rich G protein-coupled relaxin receptor RXFP1 to C1q-tumor necrosis factor-related protein 8 (CTRP8) ligand mediates increased GBM cell migration, protein kinase C pathway activation, and lysosomal protease cathepsin B production in glioblastoma progenitor cells." (PMID 37033981, 2023). "Cathepsin B(CTSB) and cathepsin L (CTSL) is also strongly expressed in various cell clusters in the glioblastoma microenvironment." (PMID 36552760, 2022). "In glioblastoma models, TQ disrupts lysosomal membrane integrity and triggers cathepsin-B release, blocking autophagic flux and promoting non-autophagic cell death." (PMID 41303508, 2025). "Conversely, in some glioblastoma models (U87MG, Gli36ΔEGFR), TQ inhibits autophagy (reduced Beclin-1 and ATG7 expression) and promotes lysosomal membrane permeabilization with cathepsin-B release, thereby sensitizing cells to temozolomide and favoring non-autophagic death pathways." (PMID 41303508, 2025).
glioblastoma (continued). "In contrast, the expression of cathepsin B was not altered in co-cultures of MSCs and other glioblastoma cell line U-87 MG, when compared to U-87 MG monocultures." (PMID 28938624, 2017). "Moreover, CTSB and CTSD activities were also not affected by UTMD in IR-treated glioblastoma cells (P > 0.05)." (PMID 35152910, 2022). "Concerning the classic lysosomal markers LAMP2 and CTSB no considerable differences were observed in LAMP2 protein and RNA expression, while slightly higher CTSB protein levels were detected in glioblastoma tumor centers compared to normal CNS tissue and infiltration zones." (PMID 26956048, 2016).